HOXD13 (homeobox D13)
Diseases named in the same sentence as HOXD13 in open-access papers (continued):
Sharing a sentence is not in itself a finding about the gene and the disease.
tumor (100 papers, 2012 to 2025). "Immune infiltration analysis indicated significant differences in the tumor microenvironment associated with HOXD13 expression levels." (PMID 39744569, 2025). "The performed statistical analysis reveals for both HOXA13, HOXC13, HOXD13 a strong association with tumor grading classification." (PMID 34208964, 2021). "HOXD13 methylation status is associated with lung adenocarcinoma prognosis, suggesting, also for this tumor, its diagnostic value." (PMID 31137568, 2019). "HOXD13 down-regulation is significantly associated with tumor size, lymph-node metastases and a poorer overall survival." (PMID 31137568, 2019). "These kinds of cells and their respective control cells were inoculated to BALB/c nude mice to observe the effects of HOXD13 on tumor growth." (PMID 34272834, 2021). "HOXD13 deregulation in human cancers mostly concerns haematological malignancies, less frequently than in other types of tumor." (PMID 31137568, 2019). "As another important member of the 13 paralogous HOX genes, the aberrant expression of HOXD13 has been reported in different tumor types." (PMID 28808656, 2017). "In contrast to DKK2, stable knock down of HOXD genes did not significantly influence bone invasiveness, although suppression of HOXD10, HOXD11 and HOXD13 seemed to slightly reduce the invasive growth potential of tumor cells in the bone marrow." (PMID 27363011, 2016). "A nude mouse xenograft tumor model was used to test the effects of HOXD13 on tumor growth in vivo." (PMID 34272834, 2021). "In vivo experiments also revealed that HOXD13 can promote tumor growth." (PMID 34272834, 2021). "However, in several tumor types, such as pancreatic and gastric cancers, HOXD13 has displayed the opposite trend being strongly down-regulated, which suggests also for this gene a dual role during tumor evolution, as oncogene and tumor suppressor." (PMID 31137568, 2019). "After serial sectioning, we observed that A673 sh.HOXD10 and sh.control tumor nodules in lungs were bigger with a higher amount of necrosis than the tumor nodules after injection of A673 cells with stable HOXD11 and HOXD13 knock down." (PMID 27363011, 2016). "A673 control infectants grew to numerous confluent and necrotic tumor nodules within the lung, while A673 sh.HOXD11 and A673 sh.HOXD13 infectants revealed a significantly reduced metastatic phenotype that was statistically significant (right)." (PMID 27363011, 2016). "To further elucidate the possible contribution of posterior HOXD genes to phenotype and tumor pathology of ES we analyzed contact dependent growth of HOXD10, HOXD11 and HOXD13 shRNA infectants with an impedance-based system." (PMID 27363011, 2016). "Our data showed the absence of expression of HOXA13, HOXB13, HOXC13 and HOXD13 in the normal mucosa, a slight increase in expression in the transitional mucosa, up to in many cases over-expressed in the tumor." (PMID 30541551, 2018). "Five of the genes affected by a single technology indel (WGS) in the MSI tumor (GNAS, HOXC13, MAPK1, and ZFHX3) and two of the genes affected by a single technology indel (WGS) in the MSS tumor (GNAS and HOXD13) were also listed in the cancer gene census list of the COSMIC database." (PMID 28683819, 2017). "Like HOXD13, HOXB13 expression is restricted to the distal colon and rectum (generally at higher levels than HOXD13), and it is expressed in HPs as well as all other tumor types, with levels in distal-colon tumors that are far higher than those in their proximal-colon counterparts." (PMID 33423702, 2021). "A large IHC study performed on 4000 normal and neoplastic tissue samples, which included 79 different tumor categories, has shown that the over-expression of HOXD13 is prevalent in cancer tissues, compared to non-neoplastic samples, particularly in breast, colon and salivary glands cancers." (PMID 31137568, 2019).
tumor (continued). "Interestingly, HOXD10, HOXD11 and HOXD13 knock down significantly decreased the number of TRAP+ cells within tumor tissue while their number in bones was not affected." (PMID 27363011, 2016).
cancer (68 papers, 2015 to 2026). A tumor composed of atypical neoplastic, often pleomorphic cells that invade other tissues. "In particular, the genes belonging to HOX paralogous group 13 (HOXA13, HOXB13, HOXC13, and HOXD13) are strongly associated with cancer development and progression." (PMID 34208964, 2021). "High expression of genes such as HOXB5, HOXC11, HOXA13, HOXD13, HOXA6, and HOXC6 in certain cancers is linked to poor overall survival (OS)." (PMID 39980564, 2025). "The fact that Hox genes such as HOXD10, HOXA9, HOXD9, HOXD13 are strongly upregulated in Huh6 cells on the CAM reflect a profound reprogramming of cancer cells in a permissive, growth promoting in vivo microenvironment." (PMID 29662633, 2018). "Despite HOXD13 being implicated in various cancers, its role in OSCC has not been previously reported." (PMID 39744569, 2025). "The cancer‐promoting effect of HOXD13 in the colon is partly achieved through PTPRN2." (PMID 34272834, 2021). "Furthermore, we found reactivation of HOXD12 and HOXD13 expression in selected cancer samples and, surprisingly, a strong positive correlation between HOTAIR and HOXD12, particularly in overexpressing UC tissues (r Pearson = 0.92)." (PMID 25994132, 2015). "HOXA13, HOXD13 and HOXC6 were reported to promote cancer progression in CRC, and HOXB13 was reported to suppress tumors in CRC." (PMID 34950145, 2021). "In CRC, HOXA13, HOXD13 and HOXC6 were reported to promote cancer progression, and HOXB13 was reported to suppress tumors." (PMID 34950145, 2021). "In addition, HOXA11, HOXD13, and PCDHGB7 were confirmed as early methylated genes when human mammary epithelial cells (HMEC) converted into cancer cells in our previous study and in other studies." (PMID 31198475, 2019). "Although the entire HOX network plays a central role in cancer development and progression, the most posterior genes of the network, HOX13 paralogues (HOXA13, HOXB13, HOXC13 and HOXD13), specifically, are crucial in modulating these processes, in cooperation with co-localizing lncRNAs." (PMID 31137568, 2019).
HOXD13 also shares sentences with these, for which no sentence is quoted: hepatocellular carcinoma (21 papers); non-small cell lung carcinoma (16); autoimmune disease (13); lung carcinoma (13); melanoma (13); Sepsis (12); infection (10); rheumatoid arthritis (10); renal cell carcinoma (8); COVID-19 (7); diffuse large B-cell lymphoma (7); Arthritis (6); ovarian carcinoma (6); nasopharyngeal carcinoma (5); triple-negative breast carcinoma (5); chronic hepatitis B (4); metastatic melanoma (4); pancreatic adenocarcinoma (4); breast tumors (3); hematological malignancies (3); immune thrombocytopenia (3); liver diseases (3); lung adenocarcinoma (3); pancreatic ductal adenocarcinoma (3); rectal cancer (3); renal carcinoma (3); scarlet fever (3); syndactyly type 5 (3); systemic lupus erythematosus (3); acute lymphoblastic leukemia (2).
A further 105 diseases each share a sentence with HOXD13 in 2 papers or fewer.